MMP7 (matrix metallopeptidase 7)
Diseases named in the same sentence as MMP7 in open-access papers (continued):
Sharing a sentence is not in itself a finding about the gene and the disease.
prostate carcinoma (continued). "This shows that the intracellular Wnt/β-catenin signaling is interactive and can impact prostate cancer progression with and without the aid of other genes like androgen receptor and MMP-7." (PMID 35201496, 2021). "It is astonishing that MMP7 is not expressed in a normal prostate, whereas is overexpressed in human prostate cancer." (PMID 31671654, 2019). "Several are known biomarkers for diagnosis and prognosis of prostate cancer (APC, GSTP1, KIT, PYCARD, PGDGRB, RARB, RARRES1, and TIMP1) and some though not biomarkers, were found to be dysregulated in the disease (CDKN1B, MMP7, and MMP9)." (PMID 24626295, 2014). "In a study aimed at investigating serum levels of various MMPs in the prostate cancer, circulating MMP-7 was significantly elevated in individuals with distant metastases, suggesting that MMP-7 may play a role facilitating distant metastases." (PMID 24978435, 2014). "Previously, we demonstrated that matrix metalloproteinase 7 (MMP7) could cleave membrane-bound RANKL into a soluble form (sRANKL), which abate the contact-dependent nature of osteoblast-osteoclast interaction and promote osteoclast activation and subsequent osteolysis in a prostate cancer model." (PMID 29547583, 2018). "In contrast to JQ1, ivermectin also downregulated the expression of EMT genes, such as MET, MMP7, and SOX9, and did not induce EMT in prostate cancer." (PMID 36050295, 2022). "While we did not detect a separate hillock cell population within our prostate cancer epithelial cells, we did detect a distinct population representing 6.5% of all epithelial cells (872 of 13,322) characterized by expression of PIGR, MMP7, CP, and LTF (FDR q < 10e-20)." (PMID 35013146, 2022).
pancreatic cancer (56 papers, 2011 to 2025). "Specifically, Cancer cell 1 expressed Gcnt3, Mmp7, and Vsig2, which are associated with the epithelial/classical subtype of pancreatic cancer cells." (PMID 37998349, 2023). "Another study compared tumor tissues with healthy control samples revealed that MMP7 was highly predictive for advanced stage of pancreatic cancer, which strongly associated with N1 status, T3/T4 stage, moderate/poor differentiation, and perineural invasion." (PMID 30428899, 2018). "MMP-7 is reported to be expressed in the epithelia of gastrointestinal ulcers and elevated levels of serum MMP-7 in pancreatic carcinoma patients is associated to decreased survival." (PMID 27561093, 2016). "These two hub genes, ITGA2 and MMP7, may act as potential diagnostic and therapeutic biomarkers in pancreatic cancer patients." (PMID 30428899, 2018). "Thus, the increased Mmp-7 expression in our data might be associated with the rapid growth of pancreatic tumors in S100a4-Cre; Ext1f/f mice." (PMID 36809261, 2023). "In pancreatic cancers, the knock-out of MMP-7 in genetically engineered murine models resulted in decreased lymph node metastasis formation." (PMID 39941724, 2025). "Regarding their role as biomarkers in Pancreatic cancer, combining MMP-7 with CA19-9 in periampullary carcinoma patients achieved a 100% positive predictive value." (PMID 39575418, 2024). "Specifically, MMP‐7 is overexpressed in PanIN and was shown to be upregulated approximately 10‐fold in pancreatic cancer." (PMID 39263943, 2024). "Since the MMP‐7‐induced shedding of SDC1 ectodomain was previously observed in cultured pancreatic cancer cell lines, it is possible that the increased serum SDC1 level in our cohort was related to MMP‐7." (PMID 39263943, 2024). "MMP-7 is an important regulator of tumor formation in pancreatic cancer, and elevated MMP-7 levels correlate with metastasis and/or survival." (PMID 36809261, 2023). "Many gastrointestinal malignancies demonstrate overexpression of MMP7 including cancer of the pancreas." (PMID 38131168, 2023). "Numerous studies have showed that MMP-7 expression is elevated in pancreatic cancer compared to that in patients with pancreatitis and healthy individuals, and many studies have correlated MMP-7 expression levels with cancer metastasis and survival." (PMID 36809261, 2023). "Western blotting was used to establish the presence of MMP-7 in pancreatic cancer cell lines AsPC-1, Su86.86, BxPC-3, and CFPAC-1." (PMID 33918254, 2021). "In sum, ablation of MMP7 through GSM-192 in pancreatic cancer cell lines stabilized FasL expression and induced apoptosis, and reduced viability." (PMID 33918254, 2021). "Our initial experiments with lentiviral silencing of MMP-7 in vitro in PDAC cells indicated the importance of MMP-7 in pancreatic cancer cell viability." (PMID 33918254, 2021). "In pancreatic cancer, serum MMP-7 was recently shown to be a pre-operative prognostic marker, as its increased expression correlated with unresectable disease." (PMID 33918254, 2021). "The resultant anti MMP-7 mAb GSM-192 induced pancreatic cancer cell apoptosis, reduced migration and improved efficacy of chemotherapeutics." (PMID 33918254, 2021). "The MMP-7 level was significantly higher in pancreatic cancer than in the normal pancreas and was related with reduced survival." (PMID 32751899, 2020). "Researchers analyzed levels of MMP-7 in plasma and pancreatic juice of 94 patients (63 with pancreatic neoplasm, 31 with chronic pancreatitis)." (PMID 32751899, 2020). "It has been reported that Stat3 was a critical factor to facilitate precursor formation and enforced MMP7 expression in pancreatic cancer cells, while MMP7 level was correlated with metastasis and survival in pancreatic cancer patients." (PMID 30428899, 2018). "In concert with this finding, ERK1/2 activation induces MMP-7 expression in human brain gliomas, colon and pancreatic cancer cells." (PMID 25823818, 2015).
pancreatic cancer (continued). "Subgroup ROC analysis of stage II – IV pancreatic cancer revealed similar results for MMP-7 and MMP-12." (PMID 25483099, 2014). "Since MMP-7 is significantly overexpressed in pancreatic cancer samples when compared to pseudotumoral chronic pancreatitis, we further determined if PTE, PA, DPA and PPAC inhibit MMP-7 at the translation level as well." (PMID 23588713, 2013). "In pancreatic cancer, MMP-7 has been shown to be involved in tumor cell dissociation from the original site and subsequently gain invasion capacity." (PMID 21991388, 2011). "In the current study, we showed that knockdown of STAT3 expression decreased MMP-7 expression in pancreatic cancer cells and nude mouse xenografts." (PMID 21991388, 2011). "In ours study, we found that STAT3 inhibition can reduce MMP-7 expression in pancreatic cancer cells." (PMID 21991388, 2011). "MMP-7 also serves as a biomarker for various diseases, such as pancreatic cancer." (PMID 41002342, 2025). "In addition, knockdown of STAT3 expression in pancreatic cancer cells significantly inhibited cell invasion and MMP‐7 expression." (PMID 41425852, 2025). "MMP-7 expression was significantly increased in the pancreatic tumors of S100a4-Cre; Ext1f/f mice." (PMID 36809261, 2023). "MMP-7 is assumed to be an important factor in the growth of pancreatic cancer, and the increased expression of MMP-7 in S100a4-Cre; Ext1f/f mice may have led to increased tumor growth." (PMID 36809261, 2023). "Associations between some proteins [e.g. matrix metalloproteinase-7 (MMP7), hepatocyte growth factor (HGF) and tumour necrosis factor receptor superfamily member 9 [TNFRSF9)] and risk of pancreatic cancer were time-varying, with higher levels associated with higher short-term risk." (PMID 35064782, 2022). "We tested whether the ablation of MMP-7 can affect the survival of the mono-cultured pancreatic cancer cells and carried out MMP-7 lentiviral silencing in AsPC-1 cells." (PMID 33918254, 2021). "Similarly, GSM-192-mediated MMP-7 inhibition on pancreatic cancer cells led to induction of cell death." (PMID 33918254, 2021). "Taken together, MMP3 and MMP7 might be involved in the migration and invasion of pancreatic cancer induced by YY1 targeting TPPP." (PMID 31631174, 2019). "STAT3 activity is also necessary for pancreatic cancer cell invasion via MMP7." (PMID 27556697, 2016). "Not surprisingly, MMP-7 is linked to the disease progression in oral squamous cell carcinoma, prostate cancer, pancreatic cancer, colon cancer, breast cancer and non-small cell lung cancer." (PMID 25588786, 2015). "Thus, pancreatic cancer cells were sensitive to ablation of MMP-7." (PMID 33918254, 2021). "Moreover, MMP-7 is found in chronic pancreatitis and in pancreatic carcinoma." (PMID 27561093, 2016). "Moreover, we identified MMP-7 as a target of P. cocos triterpenes in pancreatic cancer cells." (PMID 23588713, 2013). "In pancreatic stellate cells, the major sources of CAFs in pancreatic cancer, RLN2 induced MMP-1 and MMP-7 expression." (PMID 40666525, 2025). "In pancreatic cancer cell lines, PKD2 is known to regulate the secretion of MMP-2, MMP-7 and MMP-9 via a multiprotein complex with ARF1 and ARL1, and Arfaptin2,28,76 aiding the invasion of cells in vitro and in vivo." (PMID 38323010, 2024). "It has also been demonstrated that PKD2 mediates cell invasion through the expression and secretion of MMP-1 in glioblastoma and MMP-7 and MMP-9 in pancreatic cancer." (PMID 39408603, 2024). "Further studies when detecting CA19-9, MMP7, and MUC4 markers characteristic of pancreatic cancer using SERS at a wavelength of 785 nm showed the great potential of the method for early diagnosis of the disease." (PMID 37232929, 2023). "A parafilm mask was applied onto an Au-coated slide to define spots for the immobilization of antibodies against carbohydrate antigen 19-9 (CA 19-9) and matrix metalloproteinase-7 (MMP-7), two pancreatic cancer markers." (PMID 37241360, 2023).
pancreatic cancer (continued). "Studies have shown that MMP-1, MMP-2, MMP-7, MMP-9, membrane type 1-MMP (MT1-MMP), MT2-MMP, and MT3-MMP are overexpressed in pancreatic cancer tumors, while MMP-2, MMP-7, and MMP-9 have been identified as potential biomarkers of pancreatic cancer." (PMID 34809634, 2021). "In pancreatic cancer cells, the p38 MAPK pathway regulates MMP-7 activity, which is in turn responsible for the enhanced cancer cell motility and invasion." (PMID 29954442, 2018). "In corresponding serum samples, we identified serum-derived MMP-7 and MMP-12 as strong classifiers to diagnose patients and tumor-derived PDGF-BB and MMP-1 as potential prognostic biomarkers in pancreatic cancer." (PMID 25483099, 2014). "Among those, MMP-7 and MMP-12 displayed high sensitivity and specificity in discriminating between serum samples of pancreatic cancer patients and healthy donors." (PMID 25483099, 2014). "ROC analysis of corresponding serum samples reveals MMP-7 and MMP-12 as strong classifiers for the diagnosis of patients with pancreatic cancer vs. healthy control donors." (PMID 25483099, 2014). "Even in a small subgroup of patients with early stage pancreatic cancer (UICC II), MMP-7 and MMP-12 were good classifiers to distinguish between patients with pancreatic cancer and healthy donors." (PMID 25483099, 2014). "PTE as well as PA, DPA and PPAC inhibit growth of pancreatic cancer cells and PTE and PA significantly suppress invasive behavior of BxPc-3 cells by inhibiting expression of MMP-7." (PMID 23588713, 2013). "Exogenous MMP-7 treatment has also been reported to promote EGFR-activated MEK signaling, as demonstrated by increase in p-EGFR, p-MEK, and p-ERK in pancreatic cancer cells." (PMID 24273653, 2013). "MMP1, MMP2, MMP7, and MMP9 have also been shown to be expressed in pancreatic tumor, but the effect of cysteamine on protein and mRNA levels for all these MMPs was not examined except for MMP9." (PMID 22532830, 2012). "A cancer vaccine that induces neutralizing antibodies to gastrin was shown to improve survival in a murine model of pancreatic cancer and reduce metastases by decreasing components of the metastases cascade and EMT, including protein expression of paxillin, β-catenin, and MMP-7." (PMID 36614194, 2023). "One study has demonstrated that multiplex detection of pancreatic biomarkers CA19-9, MMP7, and MUC4 in sera samples were of high sensitivity, which may act as the critical biomarker in diagnosis of pancreatic cancer." (PMID 30428899, 2018). "Further, MMP-7 (matrilysin) triggers the invasive and metastatic capacity of pancreatic ductal adenocarcinoma cells via a STAT3-dependent mechanism that is also demonstrated in the prostate, breast and pancreatic cancer cell lines." (PMID 28418923, 2017). "To understand whether and which types of MMPs were involved in the pancreatic cancer cell invasion triggered by leptin, we analyzed the expression change of MMP-2, MMP-7, MMP-9 and MMP-13 before and after leptin treatment." (PMID 25948792, 2015). "Furthermore, aberrant expression of Notch induced by MMP-7 and ADMA metalloproteinase conjunct with KRAS mutation can prompt rapid reprogramming of acinar-to-ductal metaplasia (ADM), which has been hypothesized to play cardinal role in the evolvement of pancreatic cancer." (PMID 24587996, 2014). "In another study by the Seufferlein group, PKD2 was upregulated in pancreatic cancer, and ectopic expression of PKD2 significantly enhanced invasion of pancreatic cancer cells in the surrounding three-dimensional ECM through stimulating expression and secretion of MMP-7 and MMP-9." (PMID 33807058, 2021). "It has been reported that SIRT1 is overexpressed in pancreatic cancer tissues and is a promoter of the occurrence and metastasis of pancreatic cancer; however, SIRT1 has the opposite effect in oral squamous cell carcinoma, which inhibits EMT through the SIRT1/Smad4/MMP7 pathway." (PMID 34934771, 2021).
pancreatic cancer (continued). "Moreover, the tumors expressed some well-established markers of human pancreatic cancer, including the ductal markers CK19, mucin 5 (Muc5), matrix metalloproteinase 7 (MMP7), and hairy and enhancer of split 1 (Hes1), the indicator of the active Notch signaling pathway." (PMID 30910991, 2019). "In addition, pancreatic cancer cells could stimulate the CAFs to produce more MMPs such as MMP-2, MMP-7, MMP-9, and MMP-11 which are used for ECM degradation and are conducive for MICs immigrating through the ECM." (PMID 24587996, 2014). "Therefore, MMP-7 is a suitable target involved in disease progression and the downregulation of MMP-7 expression by PA may be a useful strategy for pancreatic cancer metastasis intervention." (PMID 23588713, 2013). "Although our experiments did not clarify the localization of MMP-7 and HS, the reduction of HS specifically upregulates MMP-7 expression in the pancreatic cancer stroma." (PMID 36809261, 2023). "In the present study, we compared the expression levels of MMP-2, MMP-7, MMP-9 and MMP-13 in pancreatic cancer cells with and without leptin treatment." (PMID 25948792, 2015).
lung cancer (51 papers, 2011 to 2026). A malignant neoplasm involving the lung. "The role of EMT biomarkers FN1 and VIM and the matric metalloproteinases, MMP-9 and MMP-7, in lung cancer in the background of ALK mutation is under study." (PMID 33091333, 2021). "The reduced spreading effect and cell motility caused by miR-326 in lung cancer cells was revealed to be associated with the inhibition of the protein expression of cell migration and invasion molecules MMP-7 and MMP-9." (PMID 26840018, 2016). "The Cancer Genome Atlas (TCGA) datasets show a strong association between loss of fibulin-5 expression and poor outcomes of lung cancer patients, and also activation of the Wnt target genes MMP-7 and c-Myc." (PMID 25909283, 2015). "Our meta-analysis sheds light on the association between MMP-7 protein expression and lung cancer progression, using a comprehensive and systematic approach based on previously published studies." (PMID 25588786, 2015). "EFEMP1 is associated with decreased MMP-2 and MMP-7 levels in lung cancer and MMP-2 and MMP-9 levels in endometrial carcinoma, which are also observed in highly metastasizing and rapidly expanding tumors." (PMID 25987128, 2015). "In this study, we found that loss of fibulin-5 expression in lung cancer is strongly associated with accumulation of β-catenin and activation of MMP-7 and c-Myc." (PMID 25909283, 2015). "Subgroup analysis showed that age was not the factor influencing the associations between histologic grade, LN metastasis and MMP-7 expression in lung cancer patients, as both under 60 and over 60 age groups showed strong correlations (all P <0.05)." (PMID 25588786, 2015). "Using human biopsy samples, clinical transcriptomic datasets and mouse models, we identify matrix metalloproteinase-7 (MMP-7) as a specific biomarker of senescence in lung cancer and bleomycin-induced fibrosis." (PMID 42129475, 2026). "This approach is emerging as a promising targeted intervention to obstruct lung cancer advancement by modulating the regulatory effects of MMP7 on essential oncogenes and tumour suppressor genes." (PMID 39304978, 2024). "TMEM196 overexpression suppressed the expression of MMP2, and of MMP7 in lung cancer cells, whereas TMEM196 knockdown had the opposite effect." (PMID 37367036, 2023). "In this study, we found that alectinib and lorlatinib significantly reduced the expression of VIM, FN1, MMP-9, and MMP-7 and that finally inhibited the metastasis of lung cancer cells." (PMID 33091333, 2021). "FBLN5 was discovered to be a suppressor of lung cancer invasion and metastasis via inhibiting MMP-7." (PMID 34976811, 2021). "In lung cancer, down-regulation of fibulin-3 enhances invasion and metastasis via Wnt/β-catenin activation and matrix metalloproteinase-7 (MMP-7) expression." (PMID 33226065, 2021). "For example, Kaiso can cause transcriptional repression of unmethylated Matrix Metallopeptidase 7 (MMP7) and Cyclin D1 (CCND1) genes as well as methylated Metastasis Associated 1 family member 2 (MTA2) gene in lung cancer." (PMID 31245293, 2019). "Other stroma-derived molecules have been found to be specific for certain cancer oncotypes, such as MMP7 and osteopontin for urological and lung cancer, respectively." (PMID 30678058, 2019). "This confirms that the transactivating effects were reversed in A549 lung cancer cells by a mAChR3 inhibitor and MMP7 neutralizing antibody." (PMID 30925742, 2019). "MMP-2 holds a role in lung cancer angiogenesis mediated by vascular endothelial growth factor expression and also in the invasive behavior of tumor cells, as for MMP-7." (PMID 29207990, 2017). "On the contrary, EFEMP1 inhibited lung cancer cell invasion and metastasis and suppressed MMP-7 expression by activating Wnt/β-catenin signaling." (PMID 27351229, 2016). "Epigenetic silencing of EFEMP1 promotes lung cancer invasion and metastasis by activating MMP-7 expression." (PMID 25676403, 2015).